TSC22D4 (TSC22 domain family member 4)
Description:
Binds DNA and acts as a transcriptional repressor. Involved in the regulation of systematic glucose homeostasis and insulin sensitivity, via transcriptional repression of downstream insulin signaling targets such as OBP2A/LCN13 (By similarity). Acts as a negative regulator of lipogenic gene expression in hepatocytes and thereby mediates the control of very low-density lipoprotein release. May play a role in neurite elongation and survival (By similarity).
Synonyms: THG1; THG-1; TILZ2
Tractability: PROTAC: ubiquitination databases record sites on it; its protein half-life has been measured.
Gene: Protein-coding gene on chromosome 7 (100,466,519 to 100,479,232, reverse strand). Ensembl gene ENSG00000166925.
Subcellular location: Nucleus; Cytoplasm; Cell projection, dendrite; Synapse
Subcellular location (Human Protein Atlas): Cytosol
Gene Ontology:
Molecular function: protein binding
Biological process: glucose homeostasis; negative regulation of DNA-templated transcription; negative regulation of transcription by RNA polymerase II; neuron cellular homeostasis; neuron projection extension; response to osmotic stress; regulation of transcription by RNA polymerase II
Cellular component: cytoplasm; dendrite; nucleus; synapse
Genetic constraint (gnomAD): Loss-of-function variants: 5 observed, 19.36 expected, observed/expected ratio (o/e) 0.26, 90% interval 0.13 to 0.54. The upper end of that interval is the gene's LOEUF score, 0.54, which puts it in group 2 of 6, group 1 being the genes least tolerant of losing a copy. Missense variants: 469 observed, 502.59 expected, observed/expected ratio (o/e) 0.93, 90% interval 0.86 to 1.01. Synonymous variants: 245 observed, 219.42 expected, observed/expected ratio (o/e) 1.12, 90% interval 1 to 1.24.
Homologues: Orthologues: chimpanzee TSC22D4 (99% identical), pig TSC22D4 (87% identical), guinea pig TSC22D4 (86% identical), mouse Tsc22d4 (84% identical), macaque TSC22D4 (83% identical), dog TSC22D4 (74% identical), rat Tsc22d4 (71% identical), mouse Gm57848 (70% identical), rabbit TSC22D4 (69% identical), Caenorhabditis elegans Y48C3A.12 (22% identical), Drosophila melanogaster bun (19% identical), Caenorhabditis elegans tsct-1 (16% identical). Paralogues in human: TSC22D1 (36% identical), TSC22D2 (33% identical), TSC22D3 (20% identical).
Diseases named in the same sentence as TSC22D4 in open-access papers:
TSC22D4 is named in the same sentence as 22 diseases in open-access papers, as found by Europe PMC text mining. Sharing a sentence is not in itself a finding about the gene and the disease. The quoted sentences say what the papers report.
Insulin resistance (3 papers, 2013 to 2021). Increased resistance towards insulin, that is, diminished effectiveness of insulin in reducing blood glucose levels. "Taken together, these findings demonstrate that inhibition of LCN13 acts as one major functional downstream target of TSC22D4 in the control of (diabetic) glucose intolerance and insulin resistance in vivo." (PMID 27827363, 2016). "Hepatic TSC22D4 inhibition both prevents and reverses hyperglycaemia, glucose intolerance and insulin resistance in diabetes mouse models." (PMID 27827363, 2016). "Single TSC22D4 knockdown significantly ameliorated glucose intolerance, insulin resistance and hyperglycaemia in db/db mice." (PMID 27827363, 2016). "Interestingly hepatic TSC22D4 expression positively correlates with insulin resistance in obese patients and liver specific TSC22D4 knockdown in diabetic mice improves glucose homeostasis and insulin resistance." (PMID 34319011, 2021). "Remarkably simultaneous knockdown of hepatic LCN13 and TSC22D4 expression by double adenoviral shRNA delivery partially re-induced systemic glucose intolerance as well as dysfunctional glucose homeostasis and insulin resistance in diabetic mice." (PMID 27827363, 2016).
diabetes (2 papers, 2016 to 2025). "Notably, patients with diabetes show elevated levels of TSC22D4 expression in the liver, linked to reduced insulin sensitivity, high blood sugar levels, and lower LCN13 serum concentrations." (PMID 39906612, 2025). "In mouse models of diabetes, inhibiting the activity of TSC22D4 in the liver can prevent and reverse hyperglycemia, glucose intolerance, and insulin resistance." (PMID 39906612, 2025). "Here, the authors show TSC22D4 inhibition improves insulin sensitivity in several mouse models of diabetes, which they attribute at least in part to the induction of secreted LCN13." (PMID 27827363, 2016). "We now identify the hepatic TSC22D4 as a potent regulator of insulin sensitivity in both murine and human diabetes, acting—at least in part—through the secreted factor lipocalin LCN13." (PMID 27827363, 2016). "The efficient and acute improvements in diabetic glucose homeostasis next prompted us to test for a putative diabetes prevention potential of hepatic TSC22D4 inhibition." (PMID 27827363, 2016). "Our results establish TSC22D4 as a checkpoint in systemic glucose metabolism in both mice and humans, and propose TSC22D4 inhibition as an insulin sensitizing option in diabetes therapy." (PMID 27827363, 2016). "TSC22D4 thus represents a previously unknown checkpoint in inter-organ communication and systemic metabolic control and may serve as an attractive target in insulin sensitizing diabetes therapies." (PMID 27827363, 2016).
hypertriglyceridemia (2 papers, 2013 to 2016). A laboratory test result indicating elevated triglyceride concentration in the blood. "Liver-specific ablation of TSC22D4 triggered hypertriglyceridemia through the induction of hepatic VLDL secretion." (PMID 23307490, 2013).
Obesity (2 papers, 2013 to 2016). Accumulation of substantial excess body fat. "The regulation of TSC22D4 in response to tumour stress and its implications in liver cell metabolism might thereby exemplify a common transcriptional node in the documented link between obesity-related dyslipidemia and an increased risk for certain cancer entities." (PMID 23307490, 2013). "Therefore, we chronically knocked-down TSC22D4 specifically in hepatocytes of young (5 weeks old) db/db mice that still showed no signs of obesity and metabolic dysfunction." (PMID 27827363, 2016).
Cachexia (1 paper, 2013). Severe weight loss, wasting of muscle, loss of appetite, and general debility related to a chronic disease. "Our study identifies TSC22D4 as a cachexia-inducible regulator of hepatic VLDL secretion and a molecular determinant of circulating TG levels, associated with a regulatory function in the control of lipogenic gene expression in the liver." (PMID 23307490, 2013). "In line with the assumption that TSC22D4 mediates parts of the metabolic liver phenotype during cancer cachexia, inhibition of lipogenic gene expression in primary hepatocytes by cachexia-inducing conditioned C26 or B16 melanoma tumour cell supernatants was rescued by TSC22D4 knockdown." (PMID 23307490, 2013). "Therefore, hepatic TSC22D4 activity may represent a molecular rationale for peripheral energy deprivation in subjects with metabolic wasting diseases, including cancer cachexia." (PMID 23307490, 2013).
esophageal squamous cell carcinoma (1 paper, 2023). Esophageal squamous cell carcinoma (ESCC) is a type of esophageal carcinoma (EC) that can affect any part of the esophagus, but is usually located in the upper or middle third. "TSC22D4, also known as THG-1, was reported to promote esophageal squamous cell carcinoma cell tumorsphere growth." (PMID 37237254, 2023).
Glucose intolerance (1 paper, 2016). Glucose intolerance (GI) can be defined as dysglycemia that comprises both prediabetes and diabetes. "Thus, we next tested the hypothesis that hepatic TSC22D4 inhibition could serve as a novel approach to counteract diabetic hyperglycaemia and glucose intolerance." (PMID 27827363, 2016).
hepatoma (1 paper, 2016). "Indeed, siRNA-mediated TSC22D4 knockdown in hepatoma cells transfected with Lcn 13 luciferase reporter constructs carrying the identified TSC22D4-binding sites within the Lcn 13 locus induced reporter gene activities." (PMID 27827363, 2016).
hyperglycaemia (1 paper, 2016). "Human diabetic patients display elevated hepatic TSC22D4 expression, which correlates with decreased insulin sensitivity, hyperglycaemia and LCN13 serum levels." (PMID 27827363, 2016).
nonalcoholic fatty liver disease (1 paper, 2025). "Recently, our laboratory identified hepatic TSC22D4 as an environmental sensor that contributes to diabetic hyperglycemia, insulin resistance exacerbating nonalcoholic fatty liver disease (NAFLD) and liver fibrosis associated pathologies." (PMID 40679946, 2025).
cancer (4 papers, 2013 to 2024). A tumor composed of atypical neoplastic, often pleomorphic cells that invade other tissues. "TSC22D4 regulates hepatic lipoprotein production, but has so far mainly been studied in the context of cancer cachexia." (PMID 27827363, 2016). "Our data now provide first insights into tissue-specific functions of the TSC22D4 protein with further implications for the pathogenesis of cancer-related cachexia." (PMID 23307490, 2013). "Furthermore, hepatic TSC22D4 expression levels were correlated with the degree of body weight loss and VLDL hypo-secretion in cancer cachexia, and TSC22D4 deficiency rescued tumour cell-induced metabolic dysfunction in hepatocytes." (PMID 23307490, 2013).
tumour (3 papers, 2013 to 2016). "The hepatic induction of TSC22D4 and its correlation with body weight loss in the tumour-bearing state is intriguing, as TSC22D4 belongs to a family of suspected tumour suppressor genes." (PMID 23307490, 2013). "Along these lines, hepatic TSC22D4 levels were indeed found to significantly correlate with the degree of body weight loss upon tumour development in this study." (PMID 23307490, 2013). "Livers of tumour-bearing mice had elevated levels of TSC22D4 and hepatic knockdown of TSC22D4 acutely led to the induction of lipogenic genes." (PMID 27827363, 2016). "The results of our study are consistent with a model, in which tumour stress triggers the upregulation of hepatic TSC22D4 gene expression." (PMID 23307490, 2013). "In contrast, TSC22D4 mRNA levels positively correlated with the degree of body weight loss and negatively correlated with hepatic VLDL secretion in tumour bearing versus control animals." (PMID 23307490, 2013). "Consistent with the cachectic phenotype in tumour-carrying animals, levels of TSC22D4 were found to be significantly upregulated in livers of MCD-fed animals as compared to controls." (PMID 23307490, 2013). "It is tempting to speculate that the regulation of TSC22D4 expression is sensitive to certain metabolites, including amino acids, as one-carbon unit deficiency may be a common feature between the MCD and C26 tumour models." (PMID 23307490, 2013). "The expression of many genes like TSC22D4, POLR2J, PPP1R, and C6ORF47 was dependent on the aggressiveness of the tumor." (PMID 27340651, 2013). "Given the metabolic control function of TSC22D4 as demonstrated by the present study, it is tempting to speculate that TSC22 proteins may represent a family of transcriptional regulators that is broadly involved in the control of proliferative and metabolic pathways during tumour development." (PMID 23307490, 2013).
TSC22D4 also shares sentences with these, for which no sentence is quoted: bipolar disorder (1 paper); breast carcinoma (1); ciliopathies (1); dyslipidemia (1); Hepatic steatosis (1); Hyperinsulinemia (1); hypobetalipoproteinemia (1); hypoglycaemia (1); melanoma (1); memory impairment (1).